MMP11 (matrix metallopeptidase 11)
Diseases named in the same sentence as MMP11 in open-access papers (continued):
Sharing a sentence is not in itself a finding about the gene and the disease.
diabetes (4 papers, 2020 to 2024). "The remaining 2 dysregulated genes—Mmp11 and Abhd8—have not been associated with activities in the brain but have been implicated in diabetes (Mmp11) and lipid metabolism (Abhd8)." (PMID 31912136, 2020). "Therefore, MMP-2, MMP-9, MMP-11, MMP-13, and TIMP-4 could be important biomarkers to evaluate in diabetes and associated disorders." (PMID 33419373, 2020). "Moreover, the significant alteration in levels of MMP1, MMP3, MMP11, CHI3L1 and VEGF-A in non-diabetic fibroblasts between day 3 and day 7 after the wound were all abolished in diabetic M1 fibroblasts, and their expression levels were also significantly lower in diabetes." (PMID 38270651, 2024).
glioma (4 papers, 2013 to 2025). A benign or malignant brain and spinal cord tumor that arises from glial cells (astrocytes, oligodendrocytes, ependymal cells). "Upregulated genes, such as EGFR and MYO1C, are associated with glioma cell proliferation and migration, whereas downregulated genes such as MMP11 and SREBF1 are related to cell adhesion and lipid metabolism (bottom)." (PMID 29587824, 2018). "Dysregulated genes observed in the MNF cohort included matrix metalloproteinase (MMP)-11 and 14, which are involved in glioma growth and angiogenesis and the development of high-grade astrocytic tumors." (PMID 25505565, 2013). "For example, MMP-11 and MMP-19 have been observed to be upregulated in certain high-grade gliomas and are thought to participate in altering the physical properties of the ECM, enabling cancer cells to migrate more freely." (PMID 40265458, 2025). "For example, bioinformatics analyses have shown that certain MMPs, such as MMP-1, MMP-11, MMP-19, and MMP-21, are consistently upregulated in GBM compared to normal brain tissue, suggesting that they may serve as biomarkers for diagnosis and prognosis in high-grade gliomas." (PMID 40265458, 2025).
head and neck cancer (4 papers, 2011 to 2024). A primary or metastatic malignant neoplasm affecting the head and neck. "Expression of MMP-11 in the head and neck cancers, on the other hand, was scarcely investigated in the literature." (PMID 28427180, 2017). "As has been reported previously in breast and head and neck cancer, there were no obvious associations among the degree of tumor differentiation, MMP-11 protein level, sex and age." (PMID 21513571, 2011).
metabolic syndrome (4 papers, 2016 to 2024). A cluster of metabolic risk factors for CARDIOVASCULAR DISEASES and TYPE 2 DIABETES MELLITUS. "Based on the lncRNA-mRNA co-expression network analysis, MMP11, which highly correlated with LINC01561-201, has been reported to strikingly protect against T2DM, while MMP11 deficient mice presented hallmarks of metabolic syndrome." (PMID 38172847, 2024). "Indeed, our group has demonstrated that mice deficient in MMP11 develop features of the metabolic syndrome, with increased triglyceride accumulation in the liver reminiscent of hepatic steatosis." (PMID 37445827, 2023). "Strikingly, MMP11 overexpression protects against type 2 diabetes while Mmp11−/− mice exhibit hallmarks of metabolic syndrome." (PMID 27126782, 2016). "Thus, MMP11 plays an important role in glucose and lipid metabolism as MMP11 ablation in mice induces diabesity with metabolic syndrome features and insulin resistance." (PMID 27126782, 2016).
metastatic tumors (4 papers, 2006 to 2025). "We observed significantly higher concentrations of MMP11 in the samples from PCa patients with metastatic disease compared to the samples from patients with primary PCa." (PMID 40122809, 2025). "Notably, MMP14 remained consistently expressed in both primary and metastatic tumors, while MMP7 and MMP11 were predominantly expressed in the earlier stages." (PMID 40604111, 2025).
thyroid cancer (4 papers, 2015 to 2024). "Many MMP family members, such as MMP2, MMP7, MMP9, MMP11, and MMP13, have been implicated to be associated with the development and progression of thyroid cancer." (PMID 28709407, 2017). "For example, the combined signal of MMP11 and MMP19, which both cleave aggrecan and gelatin, resulted in a larger area under the curve (AUC) value than individually in thyroid cancer." (PMID 39239548, 2024). "For example, for thyroid cancer (THCA), MMP11 showed an AUC of 0.928 alone, but when combined with MMP19, multivariate analysis showed an AUC of 0.961." (PMID 31200666, 2019). "The combined signal of MMP11 and MMP19, both of which cleave aggrecan and gelatin, resulted in a higher AUC value than individually in thyroid cancer." (PMID 31200666, 2019). "MMP-11 was found negative in normal thyroid tissue and thyroid follicular cells but significantly expressed in PTC tissues and thyroid carcinoma cell lines." (PMID 25887589, 2015).
adenoma (3 papers, 2006 to 2021). A neoplasm arising from the epithelium. "In our samples, only MMP11 (stromelysin-3) was upregulated in adenocarcinoma compared with paired adenoma samples." (PMID 33648461, 2021). "The authors also found seven markers specifically able to differentiate between large adenomas and CRC (BCL3, PTGES, PPARG, MMP11, IL8, TNFSF13B, CXCR3)." (PMID 33806465, 2021).
adenomyosis (3 papers, 2022 to 2025). The growth of endometrial tissue inside the muscular wall of the uterine corpus. "MMP7 expression positively correlated with uterine volume in adenomyosis; MMP11 could be negatively associated with myometrial wall thickness ratio." (PMID 41272701, 2025). "Further, MMP7, MMP9, and MMP11 appear promising as clinically relevant discriminatory markers of adenomyosis." (PMID 41272701, 2025). "The expression of IGFBP5, an estrogen-regulated molecule and substrate of MMP11, was also the highest in adenomyosis and lowest in the co-existent group." (PMID 41272701, 2025). "MMP11 expression was observed to be the highest in the eutopic endometrium of adenomyosis patients, which could be due to increased proteolytic activity in the endo-myometrial junction of these women." (PMID 41272701, 2025). "Additionally, MMP11 inversely correlated with the myometrial wall thickness ratio in adenomyosis." (PMID 41272701, 2025). "On comparing adenomyosis patients with controls, significant differences were observed in the expression of MMP9, MMP11, SERPINA1, IGFBP5, and TIMP1 (p < 0.05); however, MMP7 and THBS1 remained comparable." (PMID 41272701, 2025). "Expression of key genes indicated enhanced ECM remodeling in adenomyosis, with MMP7, MMP9, and MMP11 emerging as potential discriminatory markers." (PMID 41272701, 2025). "While MMP7 exhibited the highest expression in the co-existent group (p < 0.0001), MMP11 and IGFBP5 showed maximum expression in women with adenomyosis (p < 0.0001)." (PMID 41272701, 2025). "We performed differential gene analysis on cluster 24 cell populations from both groups and found that the differential genes that were remarkably overexpressed in the adenomyosis pain group were SFRP4 and MMP11 (log2(FC)>2)." (PMID 36532077, 2022).
basal cell carcinoma (3 papers, 2020 to 2024). A carcinoma involving the basal cells. "Specifically, we found a population of fibroblasts (fibroblast cluster 1) marked by combined expression of POSTN (Periostin) and MMP11, a marker of fibroblasts in basal cell carcinoma." (PMID 33053333, 2020). "MMP3 and MMP11 have previously been shown to be involved in CD200 ectodomain shedding in basal cell carcinoma and thus may be involved in regulating the cleavage of CD200 in PDAC." (PMID 38619621, 2024). "In situ, CD200 underwent ectodomain shedding by metalloproteinases MMP3 and MMP11, which released biologically active soluble CD200 into the basal cell carcinoma microenvironment." (PMID 36074574, 2022).
endometrial cancer (3 papers, 2010 to 2023). Primary or metastatic malignant neoplasm involving the endometrium (mucous membrane that lines the endometrial cavity). "MMP-11 was found to have a specific function in the early stages of carcinogenesis in endometrial cancer, as high levels were detected in early cancer stages and low or no detectable levels of MMP-11 were detected in later stages." (PMID 36982551, 2023). "The expression of MMP-11, -23, -24 and -28, which was identified in our study on both, mRNA and protein level, could be related to the development of endometrial carcinoma and awaits further investigation in this cancer entity." (PMID 20942921, 2010).
esophageal cancer (3 papers, 2006 to 2021). A primary or metastatic malignant neoplasm involving the esophagus. "MMP11 was 100% specific and over 93% sensitive in colon and esophageal cancer." (PMID 31200666, 2019).
gastric adenocarcinoma (3 papers, 2011 to 2022). "The aim of the study was to evaluate the associations between the expression of MMP-11 protein in serum and response to front-line chemotherapy and prognosis in advanced gastric adenocarcinoma." (PMID 21513571, 2011). "Next, 10 ERGs associated with prognosis of gastric adenocarcinoma patients are screened out by univariate Cox regression, and 6 pivotal prognostic ERGs (MMP8, MMP11, TFDP3, MYB, F2, and CNTN1) are identified through multivariate Cox regression." (PMID 32309437, 2020). "In other words, the findings indicate that MMP-11 protein is an independent prognostic factor for patients with advanced gastric adenocarcinoma." (PMID 21513571, 2011). "This study is the first to identify a correlation between MMP-11 expression and outcome in advanced gastric adenocarcinoma patients." (PMID 21513571, 2011). "The aim of the present study was to investigate the association between serum levels of matrix metalloproteinase 11 (MMP-11) and responses to front-line chemotherapy and prognosis in advanced unresectable gastric adenocarcinoma." (PMID 21513571, 2011). "This study demonstrated that MMP-11 over-expression was consistently detected in advanced gastric adenocarcinoma." (PMID 21513571, 2011). "Currently, the impact of MMP-11 on advanced gastric adenocarcinoma is uncertain." (PMID 21513571, 2011). "The serum levels of MMP-11 protein were significantly higher in patients with advanced gastric adenocarcinoma (n = 86; median = 41.74 ng/ml; range from 10.43 to 97.37 ng/ml) than in controls (n = 20; median = 6.74 ng/ml; range from 5.71 to 8.56 ng/ml; p < 0.001)." (PMID 21513571, 2011). "We also investigated the impact of CAF markers highly clustered with COL1A1 and COL5A1 in correlation analysis, namely THBS2, FAP, INHBA, S100A4, COL11A1, or MMP11, on the outcome of CAF infiltration in stomach adenocarcinoma." (PMID 35739492, 2022). "The results demonstrate that serum MMP-11 levels are not correlated with response to front-line chemotherapy, but are correlated with lymph node status and mOS in patients with advanced gastric adenocarcinoma." (PMID 21513571, 2011).
head and neck squamous cell carcinoma (3 papers, 2019 to 2025). A squamous cell carcinoma that arises from any of the following anatomic sites: lip and oral cavity, nasal cavity, paranasal sinuses, pharynx, larynx, and salivary glands. "MMP7, MMP9, MMP11, MMP12 and MMP13 were all up-regulated in head and neck squamous cell carcinoma." (PMID 36941602, 2023).
Hepatic steatosis (3 papers, 2016 to 2023). Steatosis is a term used to denote lipid accumulation within hepatocytes. "Consistently, the livers of Mmp11-Tg mice were also protected from hepatic steatosis compared to WT livers." (PMID 27126782, 2016). "In summary, MMP11 protects from excessive weight gain and hepatic steatosis through increased lipid mobilisation and metabolism from fat and liver." (PMID 27126782, 2016).
Insulin resistance (3 papers, 2016 to 2023). Increased resistance towards insulin, that is, diminished effectiveness of insulin in reducing blood glucose levels. "It is also plausible that in response to a metabolic insult such as nutrient stress-induced insulin resistance, the organism responds by increasing MMP11 expression, perhaps in an attempt to restore metabolic homeostasis." (PMID 37445827, 2023). "The question that arises from these observations is the following: does MMP11 protect from insulin resistance, or is it a deleterious factor?" (PMID 37445827, 2023). "The authors conclude that dysregulation of MMP-11 expression is the initial stage of the process of adipose tissue dysfunction, which may, consequently, lead to problems with insulin resistance." (PMID 38203373, 2023).
invasive ductal carcinoma (3 papers, 2015 to 2024). "MMP-11 was first recognized for its elevated expression in invasive ductal carcinoma compared to in situ carcinoma, its presence in lobular carcinoma is low." (PMID 38438841, 2024). "In other studies, MMP-11 was found expressed in tumor cells of traditional invasive ductal carcinoma, though the epithelial expression was much less constantly associated with prognosis than the stromal expression." (PMID 38438841, 2024). "Clinicopathological parameters of MMP-11 in patient with invasive ductal carcinoma of the breast from HUGH cohort." (PMID 34038440, 2021). "Another report demonstrated that high expression level of MMP-11 existed in invasive breast tumors, especially in invasive ductal carcinomas, which might provide some clues for prognosis." (PMID 26270045, 2015).
prostate tumor (3 papers, 2014 to 2019). "In addition, Andrographolide decreased prostate tumor growth, decreased matrix metalloproteinase 11 (MMP11) expression, decreased angiogenesis and altered DNA repair genes such as BRCA2, ATM, BRIP1 in vivo." (PMID 30800220, 2019). "To determine the role of miR-135a and its targets in the pathogenesis of PCa, we investigated miR-135a, RBAK and MMP11 expression levels in prostate tumors compared to normal prostate tissues using two publicly available gene expression database: GSE21036 and GSE6919." (PMID 27323416, 2016).
Stroke (3 papers, 2007 to 2024). Sudden impairment of blood flow to a part of the brain due to occlusion or rupture of an artery to the brain. "Using Western blotting and immunohistochemistry, PAK1, INI1 and MMP11 protein expression and localization was determined in the contralateral and ipsilateral brain areas of individual stroke patients and rats subjected to MCAO, and in HBMEC and HFN exposed to OGD and reperfusion." (PMID 17997827, 2007). "For MMP11, RT-PCR data agreed with the findings from the microarray study, showing increased mRNA levels in infarcted and peri-infarcted tissue from patients surviving 2–20 days following stroke." (PMID 17997827, 2007). "Furthermore, female MMP-3 KO stroke brains showed decreased expression of apoptosis signaling genes Casp6, Tnfrsf1b, Tnfrsf1a, and Tnf, and downregulated expression of matrix metalloprotease genes Mmp14, Mmp9, and Mmp11." (PMID 39000490, 2024). "Amongst these genes we examined in more detail a small subset with no prior report of a role in stroke (PAK1, MMP11 and INI1)." (PMID 17997827, 2007).
carcinoma in situ (2 papers, 1996 to 2005). "MMP11 expression in bronchial lesions starts in dysplasia and carcinoma in situ, increasing in invasive lesions, as it appears to occur in CC." (PMID 15989693, 2005). "MMP-11 characterised all carcinomas as well as carcinomas in situ but was not detectable in NHL." (PMID 8645587, 1996).
cervical squamous cell carcinoma (2 papers, 2021 to 2023). A squamous cell carcinoma arising from the cervical epithelium. "POSTN + fibroblasts showed high expression levels of several ECM remodeling genes (MMP11, CTHRC1, COL1A1, COL1A2, COL3A1, COL10A1, and COL11A1) and enriched signatures of ECM, which were consistent with the previously reported matrix CAFs (mCAFs) in cervical squamous cell carcinoma (CESC)." (PMID 37833788, 2023).
colon adenocarcinoma (2 papers, 2024 to 2025). "MMP11-targeted mRNA vaccines reversed immune tolerance and conferred anti-tumor protection in murine colon adenocarcinoma models." (PMID 40607407, 2025).
glioblastoma (2 papers, 2022 to 2023). The most malignant astrocytic tumor (WHO grade IV). "This is true especially for primary glioblastoma, since in the recurrent forms it is downregulated and, consequently, stimulates Kirsten rat sarcoma virus (K-RAS), PBX homeobox 3 (PBX3), and matrix metallopeptidase 11 (MMP11) with the result of a promotion in cell migration and invasion." (PMID 37511303, 2023).
leiomyoma (2 papers, 2007 to 2023). A well-circumscribed benign smooth muscle neoplasm characterized by the presence of spindle cells with cigar-shaped nuclei, interlacing fascicles, and a whorled pattern. "The biological importance of lower expression of these MMPs in leiomyoma is unknown; however unlike most MMPs that are secreted as inactive proenzymes and require activation, MMP-11 and MMP-28 are secreted in active forms." (PMID 17718906, 2007).
Lipedema (2 papers, 2020 to 2022). Disorder of adipose tissue characterized by symmetric and bilateral enlargement of the lower extremities due to abnormal deposition of subcutaneous fat often in obese women. "The data show a decrease in gene expression of MMP2, MMP9 and MMP11 in lipedema-differentiated spheroids as compared to lipedema-undifferentiated and healthy spheroids." (PMID 33171717, 2020). "Furthermore, the slight decrease in MMP11 expression in lipedema may contribute to excess collagen deposition, as MMP11 is known to cleave COL6A3, eventually reducing collagen deposition." (PMID 36551837, 2022). "Thus, a potential link between decreased MMP11 expression and the increase in fibrosis and adipogenesis observed in lipedema adipose tissue may have been defined." (PMID 33171717, 2020). "The deposition of collagen is under the tight control of matrix metalloproteinases (MMPs), which are expressed similarly in both lipedema and healthy spheroids, except for MMP11, which showed a (nonsignificant) decreased expression." (PMID 36551837, 2022).
lung diseases (2 papers, 2024 to 2025). "MMP11 is a matrix metalloproteinase, a class of proteolytic enzymes regulating airway remodeling in lung diseases." (PMID 40352610, 2025). "Notably, among these top expressed genes, genes such as SOX9 (SRY-Box Transcription Factor 9) and MMP11(Matrix Metallopeptidase 11) are involved in epithelial-mesenchymal transition (EMT) which is involved in many different lung diseases." (PMID 39026356, 2024).
metastatic melanoma (2 papers, 2015 to 2025). A melanoma that has spread from its primary site to another anatomic site. "Moreover they suggest that other MMPs (MMP7, MMP10, MMP11, and MMP13) might be implicated in CNS invasion by metastatic melanoma cells." (PMID 25692137, 2015).
oral squamous cell carcinoma (2 papers, 2014 to 2017). "The current study investigated the association between the clinicopathological characteristics and MMP-11 expression in oral squamous cell carcinoma (OSCC) patients." (PMID 28427180, 2017). "The current study investigated the association between the clinicopathological characteristics and plasma level of MMP-11 in oral squamous cell carcinoma (OSCC) patients." (PMID 25423087, 2014).
uterine corpus endometrial carcinoma (2 papers, 2025). A endometrial carcinoma (disease) that involves the body of uterus. "In a more recent study, the expression of MMP11 and MMP17 in uterine corpus endometrial carcinoma (UCEC) was determined, and bioinformatics tools were used to correlate their expression with patient prognosis, as they influence immune cell infiltration." (PMID 41228294, 2025). "Moreover, MMP11 and MMP17 were suggested as potential biomarkers for the prognosis of uterine corpus endometrial carcinoma." (PMID 41228294, 2025).